SLFN5 (schlafen family member 5)
Diseases named in the same sentence as SLFN5 in open-access papers (continued):
Sharing a sentence is not in itself a finding about the gene and the disease.
pancreatic cancer (4 papers, 2019 to 2024). "Thus, it is suggested that SLFN5 may play a role in pancreatic cancer and is associated with the upregulation or downregulation of the ZNF154 gene." (PMID 37771431, 2023). "Moreover, we suspect that the cell growth suppressor SLFN5 might be linked to a silenced ZNF154 in pancreatic cancer." (PMID 31683647, 2019). "Increased survival rates in pancreatic cancer patients were associated with the silencing of ZNF154, which, in turn, led to increased levels of SLFN5." (PMID 37771431, 2023). "Furthermore, exogenous expression of ZNF154 in pancreatic cancer cells revealed increased SLFN5 expression, indicating a novel link between SLFN5 and ZNF154." (PMID 38791884, 2024). "CRISPR knockout of SLFN5 in pancreatic cancer cells results in decreased PDAC growth in vitro and in vivo, supporting the hypothesis that SLFN5 is required for PDAC growth." (PMID 38791884, 2024). "Hence, we argue that SLFN5 might play a role in pancreatic cancer and is connected to up- or downregulation of the ZNF154 gene." (PMID 31683647, 2019). "Moreover, we suspect a link between a silenced ZNF154 and SLFN5 in pancreatic cancer." (PMID 31683647, 2019).
ovarian carcinoma (3 papers, 2023 to 2024). A malignant neoplasm originating from the surface ovarian epithelium. "Further, in ovarian cancer, a highly malignant gynecological cancer, SLFN5 was linked to the ability of ovarian cancer cells to migrate and invade." (PMID 38791884, 2024). "Moreover, elevated levels of SLFN5 expression are significantly associated with poor prognosis in ovarian cancer patients, and targeting SLFN5 has been found to inhibit ovarian tumor growth both in vitro and in vivo." (PMID 37771431, 2023). "The study demonstrated that silencing the SLFN5 gene led to reduced expression of EMT-related proteins in ovarian cancer cell lines." (PMID 37771431, 2023). "Additionally, in ovarian cancer, it has been indicated that SLFN5 is able to promote EMT, besides EMT and invasion movement could be significantly inhibited by SLFN5 silencing." (PMID 38035023, 2023).
prostate carcinoma (3 papers, 2021 to 2023). A carcinoma that arises from epithelial cells of the prostate gland. "Immunohistochemical analysis of prostate cancer (CRPC) specimens unveiled a noteworthy association between SLFN5 expression and disease progression, along with a substantial correlation with an elevated risk of metastasis." (PMID 37771431, 2023). "SLFN5 is also among thirty upregulated genes in docetaxel-resistant C4-2B and LNCaP prostate cancer cells." (PMID 34571887, 2021). "Consequently, depletion of SLFN5 in prostate cancer (CRPC) cells diminishes the levels of intracellular essential amino acids and disrupts mTORC1 signaling in a LAT1-dependent manner." (PMID 37771431, 2023). "The potential role of SLFN5 in other subtypes of prostate cancer awaits exploration." (PMID 34571887, 2021). "This investigation identifies SLFN5 as a novel regulator of the LAT1 amino acid transporter and a significant contributor to mTORC1 activity in castration-resistant prostate cancer." (PMID 37771431, 2023). "The direct interaction between SLFN5 and ATF4 in prostate cancer results in mTOR activation." (PMID 36900220, 2023). "Unlike the nuclear-localized SLFN5 and SLFN11, the intermediate family SLFN12, which lacks nuclear import signal and localizes to the cytoplasm, also has a differentiation effect in prostate cancer cells." (PMID 34571887, 2021).
COVID-19 (2 papers, 2024 to 2025). A disease caused by infection with severe acute respiratory syndrome coronavirus 2. "Moreover, our investigation has revealed potential shared association signals between SLFN5 expression and COVID-19 outcomes." (PMID 40759647, 2025). "Our integrative analyses, involving single-cell response eQTLs, COVID-19 GWAS, and single-cell multi-omics data of COVID-19 patients, has also revealed potential roles of SLFN5 in CD4 + T cells upon SARS-CoV-2 infection." (PMID 40759647, 2025). "To summarize, the integration of response eQTL from health and single-cell multi-omics data of COVID-19 patients unravels the genetic and epigenetic regulations of SLFN5 expression." (PMID 40759647, 2025). "As CD4+ TEM cells developed, the expression of both LAG3 and SLFN5 in COVID-19 was upregulated." (PMID 39337460, 2024). "Based on CellChat analyses, monocytes communicated predominantly with CD4+ TEM cells positively expressing PTB markers (GBP2, TRAV1-2, and ODF2L) and COVID-19 markers (LAG3 and SLFN5) in both PTB and COVID-19." (PMID 39337460, 2024).
non-small cell lung carcinoma (2 papers, 2021 to 2023). A group of at least three distinct histological types of lung cancer, including non-small cell squamous cell carcinoma, adenocarcinoma, and large cell carcinoma. "SLFN5 protein expression positively correlates with the overall survival in non-small cell lung cancer (NSCLC)." (PMID 34571887, 2021). "SLFN5 represents a promising biomarker for early-stage non-small cell lung cancer (NSCLC) patients." (PMID 37771431, 2023).
Obesity (2 papers, 2020 to 2024). Accumulation of substantial excess body fat. "Through SLFN5-regulated networks, the analysis revealed that SLFN5-regulated chemokines are involved in inflammation in adipose tissues and the liver in obesity, type 2 diabetes, and metabolic syndrome X as well as the immune system." (PMID 39310264, 2024). "Three genes (ITK, SLFN5, STK10), which have not been linked to diabetes yet, might interact with IFNG and thereby contribute to inflammatory mechanisms usually triggered by obesity." (PMID 32350386, 2020).
pancreatic ductal adenocarcinoma (2 papers, 2023 to 2026). An infiltrating adenocarcinoma that arises from the epithelial cells of the pancreas. "We provide evidence that human and murine Schlafen 5 (SLFN5) proteins are modulators of type I IFN responses and the immune response in pancreatic ductal adenocarcinoma (PDAC)." (PMID 41591829, 2026).
pneumonia (2 papers, 2024). An acute, acute and chronic, or chronic inflammation focally or diffusely affecting the lung parenchyma, caused by an infection in one or both of the lungs (by bacteria, viruses, fungi, or mycoplasma.). "These similar observations from an LPS-induced pneumonia mouse model and human A549 cells provide partial evidence that the human and mouse SLFN5 gene products are functional orthologs, at least in the context of LPS-mediated pulmonary inflammation." (PMID 38791884, 2024). "Furthermore, given the rising incidence of pneumonia in recent years, researchers have found that in a model of pneumonia induced by lipopolysaccharide (LPS), the knockout of SLFN5 mitigates LPS-triggered lung injury by modulating the JAK/STAT pathway." (PMID 39558948, 2024).
triple-negative breast carcinoma (2 papers, 2024 to 2025). An invasive breast carcinoma which is negative for expression of estrogen receptor (ER), progesterone receptor (PR), and human epidermal growth factor receptor 2 (HER2). "Of the six SLFN genes, Schlafen 5 (SLFN5) has been consistently shown to be induced by type I IFNs in these cancers, as well as in triple-negative breast cancer, as shown by others." (PMID 38791884, 2024). "Inhibiting Schlafen Family Member 5 (SLFN5) expression promotes the malignant progression and drug resistance of Triple-negative breast cancer (TNBC)." (PMID 41179284, 2025).
brain tumor (1 paper, 2023). "SLFN5 can be induced by type I interferon (IFN) in malignant brain tumor cells and acts as an inhibitor of gene transcription driven by STAT1 through direct protein interactions." (PMID 37771431, 2023). "Protein analysis revealed overexpression of SLFN5 in malignant brain tumor cells." (PMID 37771431, 2023).
HCMV infection (1 paper, 2022). "Indeed, we found that SLFN5 was down-regulated early during HCMV infection, raising the intriguing possibility that the virus differentially regulates members of this important family to maximize viral replication." (PMID 35105802, 2022).
HIV-1 infection (1 paper, 2026). The type species of lentivirus and the etiologic agent of acquired immunodeficiency syndrome (AIDS). "Our analysis revealed that the transcript encoding Schlafen family member 5 (SLFN5) was upregulated upon HIV-1 infection but with a shortened 3’ UTR due to changes in APA upon HIV-1 infection." (PMID 41405390, 2026). "The analysis of protein expression levels encoded by mRNA transcripts undergoing APA revealed that SLFN5 protein levels are upregulated upon HIV-1 infection." (PMID 41405390, 2026). "We found that the SLFN5 expression levels increase with higher viral input, indicating that HIV-1 infection induces alterations in SLFN5 expression in a dose-dependent manner." (PMID 41405390, 2026). "Across three independent HIV-1-GFP preparations, HIV-1 infection increased SLFN5 protein expression by 6-7 fold that of mock-infected cells." (PMID 41405390, 2026). "Next, to assess SLFN5 expression over time, we performed a time course of HIV-1 infection in which A549 cells were infected with HIV-1-GFP at an MOI of 2 for 0, 48, 72, or 96 h." (PMID 41405390, 2026). "SLFN5 expression increases during HIV-1 infection in A549 cells and primary cells, which is in agreement with previous observations in peripheral blood mononuclear cells." (PMID 41405390, 2026). "To verify whether the observed increase in SLFN5 expression was specifically due to productive HIV-1 infection, we repeated infections using heat-inactivated HIV-1-GFP viruses (95°C for 30 mins)." (PMID 41405390, 2026). "Furthermore, this report also shows that SLFN5 overexpression results in decreased HIV-1 infection, while decreased SLFN5 promotes HIV-1 replication, demonstrating a connection between SLFN5 expression and HIV-1 infection." (PMID 41405390, 2026). "Finally, we tested whether HIV-1 infection in CPSF6-depleted A549 cells (CPSF6-KO) had an effect on SLFN5 expression, a readout of APA regulation." (PMID 41405390, 2026). "Because HIV-1 infection mimics the phenotype observed in CPSF6-KO cells, we investigated whether CPSF6 depletion influences SLFN5 expression." (PMID 41405390, 2026). "In CPSF6-KO cells, the presence of HIV-1 infection did not produce a significant increase in SLFN5 levels compared to uninfected CPSF6-KO cells, indicating that in CPSF6-KO cells, the expression level of SLFN5, and consequently also the APA, reached its threshold." (PMID 41405390, 2026).
lung adenocarcinoma (1 paper, 2021). A carcinoma that arises from the lung and is characterized by the presence of malignant glandular epithelial cells. "The discrepancy in the reported effect of SLFN5 knockdown in A549 lung adenocarcinoma cells between these studies could reflect differences in cell passage or type between the two laboratories with phenotypic drift." (PMID 34571887, 2021).
ovarian tumor (1 paper, 2023). "SLFN5 expression levels increase with the malignant tumor grade and reach their peak in ovarian tumors." (PMID 37771431, 2023).
psoriasis (1 paper, 2025). An autoimmune condition characterized by red, well-delineated plaques with silvery scales that are usually on the extensor surfaces and scalp. "A 2019 proteomic study identified SLFN5 among a set of new disease-associated proteins in psoriasis, alongside other markers (ATM, ZNF512, SPATA13, etc.)." (PMID 41328434, 2025). "The seven genes span established–emerging–novel tiers: PRF1 and KLRC1/KLRD1 are established in psoriasis immunity; SLFN5 is a recently reported systemic inflammatory marker; BIN2/CXXC5/CAPN12 lack prior links, suggesting novelty." (PMID 41328434, 2025). "That study, which used a high-throughput SomaScan assay on patient serum, reported SLFN5 as one of the proteins elevated in psoriasis patients–particularly tied to TNF-α and interferon-driven inflammation." (PMID 41328434, 2025). "Additional Mendelian randomization analysis pinpointed seven marker genes linked to psoriasis: BIN2, CAPN12, CXXC5, KLRC1, KLRD1, PRF1, and SLFN5." (PMID 41328434, 2025). "By integrating single-cell RNA sequencing with MR analysis, we identified seven psoriasis-related genes (BIN2, CAPN12, CXXC5, KLRC1, KLRD1, PRF1, and SLFN5) that are highly expressed in CD4+ T cells." (PMID 41328434, 2025). "This antagonistic regulatory pattern suggests that CXXC5 and SLFN5 may play complementary roles in balancing CD4+ T cell activation and homeostasis, highlighting their potential functional relevance in psoriasis and other immune-related diseases." (PMID 41328434, 2025). "KLRC1, KLRD1, PRF1, BIN2, and SLFN5 showed enrichment concentrated in immune-inflammatory modules—including IL-17 signaling, the TNF/NF-κB axis, and innate immune sensor pathways (NOD-, RIG-I-, and Toll-like receptors)—consistent with psoriasis-relevant Th17/innate activation." (PMID 41328434, 2025).
renal carcinoma (1 paper, 2021). A carcinoma arising from the epithelium of the renal parenchyma or the renal pelvis. "However, the statistical effects of SLFN5 expression on survival in the subtypes of renal cancers (papillary renal cancer and chromophobe renal cancer) await exploration." (PMID 34571887, 2021). "Although SLFN5 expression has been studied in normal and cancerous renal cells, whether SLFN5 expression is downregulated or upregulated in renal carcinoma compared to adjacent non-tumor tissue has not been previously reported." (PMID 34571887, 2021).
renal chromophobe cell carcinoma (1 paper, 2021). "Our analysis of the TCGA dataset suggested that SLFN5 expression is significantly downregulated in RCC and renal papillary cell carcinoma, but it is upregulated in renal chromophobe cell carcinoma." (PMID 34571887, 2021).
stomach adenocarcinoma (1 paper, 2022). "The findings revealed that SLFN5, SLFN11, SLFN12, SLFN12L, SLFN13, and SLFN14 were expressed at higher levels in many cancers, including GC (stomach adenocarcinoma; STAD), while the SLFN14 expression levels were relatively low in all tumor and normal tissues." (PMID 36090985, 2022).
tumor (15 papers, 2018 to 2026). "Low expression of the SLFN5 protein is significantly associated with various clinical-pathological variables, including tumor diameter, T classification, N classification, and clinical staging." (PMID 37771431, 2023). "Some studies have indicated that SLFN5 is associated with apoptosis and cell cycle regulation in tumor cells." (PMID 37771431, 2023). "Yet, most authors report a connection between SLFN5 and longer survival or less invasive growth, underlining that SLFN5 is a tumor suppressor." (PMID 31683647, 2019). "Additionally, the loss of human SLFN5 leads to decreased tumor growth in vivo." (PMID 38791884, 2024). "These methodologies collectively elucidated intricate expression patterns of SLFN5 within the heterogeneous cellular landscape of the COAD tumor microenvironment (TME)." (PMID 39310264, 2024). "Single-cell analysis identified distinct SLFN5 expression patterns across different cell types within the COAD tumor microenvironment." (PMID 39310264, 2024). "As a tumor suppressor gene, SLFN5 plays a pivotal role in inhibiting tumor growth, orchestrating cell cycle regulation, and modulating the extent of cancer cell infiltration and metastasis in various malignancies." (PMID 37771431, 2023). "SLFN5 was predominantly expressed in Treg and naive T cells, which play a tumor-promoting role in cancer." (PMID 37771431, 2023). "The reduced expression of SLFN5 protein is significantly correlated with several clinical and pathological variables, including tumor diameter, T classification, N classification, and clinical staging." (PMID 37771431, 2023). "High expression of SLFN5 can promote tumor cell apoptosis and inhibit the cell cycle, thereby suppressing tumor cell proliferation." (PMID 37771431, 2023). "The results revealed a positive correlation between high expression of SLFN5 in GC and lymph node metastasis, tumor stage, and tumor grade." (PMID 37771431, 2023). "The apparently divergent roles of SLFN5 as a tumor suppressor and tumor promoter need to be investigated in further studies." (PMID 35768579, 2022). "The SLFN family expression in the PBMC indicates that SLFN5 is mainly expressed in Treg cells, which promote tumor progression." (PMID 36090985, 2022). "Consistently, we found that SLFN5 is primarily expressed in Treg and naïve T cells, which play a tumor-promoting role in cancer." (PMID 36090985, 2022). "In vitro, SLFN5 depletion strongly reduces tumor growth in CRPC by decreasing intracellular levels of essential amino acids and impairing mTORC1 signaling." (PMID 34571887, 2021). "Human SLFN5 expression is correlated with tumour cell invasion and metastasis in several malignancies." (PMID 32488136, 2020). "Human Schlafen 5 (SLFN5) has been reported to inhibit or promote cell invasion in tumours depending on their origin." (PMID 32488136, 2020). "Compared with normal controls, SLFN5 levels were significantly lower in BRCA tumour tissues (P < 0.001)." (PMID 32488136, 2020). "The precise molecular mechanisms of SLFN5 are unclear while its role in tumor growth has been fairly characterized." (PMID 31683647, 2019). "Targeting SLFN5 in certain cancers could potentially help optimize the tumor microenvironment, facilitating the recruitment of anti-tumor immune cells." (PMID 38791884, 2024). "The role of SLFN5 in tumor development may exhibit inhibitory or stimulatory effects depending on the type of tumor." (PMID 37771431, 2023). "Additionally, SLFN5 can influence tumor cell proliferation and transformation by regulating processes such as DNA replication and repair." (PMID 37771431, 2023). "However, the observed anti-tumor effects resulting from SLFN5 depletion are partially attributed to its interference with cell cycle progression." (PMID 37771431, 2023). "This indicates that SLFN5 possesses tumor-suppressive activity." (PMID 37771431, 2023).